LGR5 (leucine rich repeat containing G protein-coupled receptor 5)
Diseases named in the same sentence as LGR5 in open-access papers (continued):
Sharing a sentence is not in itself a finding about the gene and the disease.
tumor (continued). "In this study, we used CIBERSORT to analyze the correlation between LGR5 expression and immune cell infiltration in the tumor microenvironment." (PMID 41194856, 2025). "Once in the liver, these cells revert to LGR5+, initiating tumor expansion and microenvironment remodeling, including angiogenesis." (PMID 40563628, 2025). "In specific experimental model systems of CRC, the LGR5+ subset of cells appears to be both necessary and sufficient to drive tumor establishment, growth, and metastasis." (PMID 40427162, 2025). "PD‐L1 is closely related to the expression of stem cell marker genes CD44 and LGR5 in ovarian cancer and is involved in tumour recurrence." (PMID 40665579, 2025). "The CD133+/LGR5+ cancer stem cell population was significantly enriched in tumor tissues compared with adjacent normal tissues." (PMID 41423446, 2025). "Loss of adenomatous polyposis (APC) leads to excessive activation of LGR5+ stem cells, resulting in adenocarcinoma formation, indicating that LGR5+ intestinal stem cells (ISCs) are an important source of tumor cells." (PMID 41488637, 2025). "Studies in patient-derived organoid and xenograft models showed that petosemtamab more effectively inhibited tumor growth and metastasis than cetuximab, highlighting its unique capacity to exploit LGR5 upregulation as a therapeutic vulnerability." (PMID 41375018, 2025). "Using tumor samples collected from the Lgr5-specific Ythdf1cki mouse model, qPCR analysis revealed that YTHDF1 knock-in increased the expression of NOTCH1 downstream targets, including MAML1, MAML2, HES1, and HEY1." (PMID 41423446, 2025). "CSCs, which drive tumor initiation and progression, can originate from both LGR5+ stem cells and LGR5– RSCs (e.g., those expressing clusterin (CLU) and LY6A)." (PMID 39656543, 2025). "Lineage tracing showed that LGR5+ cells undergo self-renewal and sustain tumor growth, with a subset in a quiescent KI67− state." (PMID 41002429, 2025). "Beyond LGR5+ cells, evidence from lineage tracing shows that slower-dividing, radioresistant LGR5− KRT19+ stem-like populations outside the crypt base can also serve as a reservoir for tumor initiation, further highlighting SC plasticity in CRC." (PMID 41002393, 2025). "Upon ablation, tumors persist via LGR5− cells that exhibit stem cell plasticity, capable of regenerating the LGR5+ pool and sustaining tumor growth." (PMID 41002429, 2025). "A recent study found that an upregulated expression of LGR5 was significantly correlated with larger tumor diameter (> 5 cm), higher TNM stage, recurrence and metastasis in HCC." (PMID 39786609, 2025). "This study identified the existence of a novel population of LAPTM4B+ tumor stem‐like cells in addition to the classical LGR5+ tumor stem‐like cells in colorectal cancer (CRC)." (PMID 40661135, 2025). "Within the epithelial compartment, we further identified subpopulations including goblet cells, transit-amplifying cells, mature basal cells, LGR5+ stem cells, RSCs, and tumor cells based on established marker profiles." (PMID 39656543, 2025). "Instead, LGR5 interacted with TGFβ signaling pathways, triggering Smad activation to suppress tumor metastasis." (PMID 39821694, 2025). "Even at low concentrations, doxorubicin bound with RSPO1-liposomes leading to massive tumor tissue necrosis and inhibition of LGR5+ cells growth." (PMID 39821694, 2025). "This represents a potential therapeutic opportunity given the increasing interest in the role of the tumour microenvironment in supporting both LGR5(+) and (−) cancer stem cell populations." (PMID 40467544, 2025). "Inflammation and hypoxia in tumor tissue microenvironment can also potentially inhibit LGR5 protein expression through post-translational mechanisms." (PMID 39821694, 2025). "The model forms small tumor nodules composed of undifferentiated cancer cells that frequently contain LGR5-positive cells for several weeks after transplantation." (PMID 40537472, 2025).
tumor (continued). "This adaptive cell state switch enables survival under therapeutic pressure, and upon treatment withdrawal, reversion to the original LGR5+ phenotype occurs, thereby reconstituting the tumor." (PMID 41002429, 2025). "Immunohistochemical staining using α-LGR5 revealed that the residual tumour retained LGR5 expression, suggesting limitations in the half-life of the α-LGR5 bispecific or the treatment regimen." (PMID 40405910, 2025). "Leucine-rich repeat-containing G protein-coupled receptor 5 (LGR5) is a definitive marker for both normal intestinal stem cells and colorectal CSCs, playing fundamental roles in tumor initiation and progression via WNT signaling." (PMID 41256852, 2025). "The α-LGR5 antibody is highly specific and accurately detects LGR5 protein expression levels, enabling its use as a prognostic biomarker for identifying LGR5+ tumour types." (PMID 40405910, 2025). "Tumor regrowth eventually occurs upon the reappearance of LGR5+ cells that derive from the LGR5- population, mirroring the transient fetal reprogramming and YAP-dependent phenotypic plasticity that occurs in normal (non-cancerous) tissue in response to injury." (PMID 40427162, 2025). "Intestinal stem cells were a hot topic, while keywords “LGR5 (+) stem cells,” “inflammation,” and “tumor microenvironment” exhibited the strongest burst in recent years, indicating a significant research focus in the future." (PMID 41194856, 2025). "Mechanistically, leucine-rich repeat–containing GPCR5 (Lgr5+ ) cancer stem cells induced OX40 expression in tumor ECs via EGF/STAT3 signaling." (PMID 40026246, 2025). "A key advantage of targeting LGR5 is its unique overexpression in multiple, yet biologically distinct, Wnt pathway-dysregulated tumour types, including CRC, HCC, and pre-B ALL." (PMID 40405910, 2025). "Lgr5+ tumor stem cells trigger OX40 gene transcriptional activity specifically in tumor ECs via paracrine epidermal growth factor." (PMID 40026246, 2025). "Scutellarin concentration-dependently inhibited the growth and transformation of tumor stem cells HT-29CSC in vitro accompanied by a decrease in the expression of Lgr5, CK20." (PMID 39654621, 2024). "As predicted by Western blot analysis, an increased Lgr5 staining was observed in tumor samples from knockout animals compared to wild-type animals." (PMID 39456736, 2024). "We not only showed the association of MACC1 and LGR5 expression, but also demonstrated the molecular mechanism by binding of MACC1 to the gene promoter of LGR5 initiating its expression and inducing stem cell properties like tumor sphere formation." (PMID 38339354, 2024). "This binding in turn initiates the expression of LGR5 and therein induces stem cell properties, such as tumor sphere formation." (PMID 39580452, 2024). "The primary barrier to he clinical development of α-LGR5 in the three therapeutic modalities are safety studies with a suitable animal model in order to evaluate the potential for on-target/off-tumour effects on stem cell compartments that express LGR5." (PMID 39169164, 2024). "This is particularly relevant during chemotherapy treatment, where the sensitive LGR5+ve CSC population is replenished by the residual resistant tumour cells, to reinitiate tumour formation." (PMID 38319453, 2024). "The putative participation of Lgr5+ ISCs in tumor formation upon escaping the adverse effects of inflammation is also of relevance in view of the activation of the RSC state in this context." (PMID 38902475, 2024). "Salmonella, as a tumour-homing vector, and one which can preferentially invade Lgr5+ cancer stem cells, is uniquely placed to exploit this pathway in tumour control." (PMID 39558103, 2024).
tumor (continued). "We found that tumour cells in CL-BiTE-treated animals retain expression of LGR5 protein to the same extent as control-treated animals." (PMID 39169164, 2024). "Yet, tumor recurrence is observed weeks later, with differentiation of tumor cells back to LGR5+ CCSCs, showcasing the phenomenon of cellular plasticity." (PMID 38673727, 2024). "We supported this link by forced expression, knockdown or knockout of MACC1, followed by subsequent corresponding expression of stemness genes such as LGR5, as well as phenotypic features like the initiation of tumor sphere formation and clonogenicity." (PMID 38339354, 2024). "The LGR5+ve CSC signature is instead overexpressed in CMS2 tumours which represent canonical activation of WNT signalling, once again highlighting the distinct expression of the two stem cell signatures." (PMID 38319453, 2024). "The high residual tumour burden left in the CL-BiTE-treated experimental group enabled us to assess LGR5 expression levels in the tumour cells." (PMID 39169164, 2024). "Here, we report for the first time the link of MACC1, which is known to induce tumor initiation, progression and metastasis, with stemness by transcriptional expression activation of LGR5, a central stemness gene." (PMID 38339354, 2024). "Since Lgr5-positive cells can act as cancer stem cells (CSCs), their enrichment likely contributed to the knockout mice’s more aggressive tumor growth." (PMID 39456736, 2024). "These CSCs drive tumor initiation, growth, and resistance to therapy, with Lgr5 supporting proliferation and self-renewal through Wnt/β-catenin signaling." (PMID 39684755, 2024). "In all but two cases of LN metastasis, LGR5‐positive dots were detected in tumor cells, and there was a wide range of LGR5‐positive cells." (PMID 38787285, 2024). "Remarkably, high levels of LGR5 are found in NB tumor cells, and high LGR5 expression is strongly correlated with poor survival." (PMID 39065640, 2024). "Our results show that LGR5- cells display a mechanically dynamic phenotype suitable for dissemination from the primary tumor whereas LGR5+ cells display a mechanically stable and resilient phenotype suitable for extravasation and metastatic growth." (PMID 38637494, 2024). "It has been reported that selective ablation of LGR5-positive CSCs leads to tumor regression, and exposure to colon LGR5-positive CSCs enhances the effect of chemotherapy." (PMID 39727953, 2024). "Recent lineage tracing and selective cell ablation experiments have confirmed the essential role of LGR5+ CSCs in tumor and metastatic growth." (PMID 38637494, 2024). "While we observed different potencies in vivo for the three modalities in targeting pre-B-ALL tumours, these compatible therapeutic strategies give tremendous scope for accommodating the different pharmacodynamic requirements of various LGR5+ tumour types." (PMID 39169164, 2024). "For instance, we have demonstrated that human tumour cell lines that express higher levels of LGR5 are more vulnerable to all three modalities." (PMID 39169164, 2024). "The percentage of Lgr5-expressing cells with c-Src phosphorylation in KO tumor tissues was decreased about 2-fold compared to AKP tissues." (PMID 38659853, 2024). "Through the application of CRISPR-Cas9 technology, Shimokawa and team revealed that targeting LGR5+ CCSCs for elimination in CRC human organoids results in tumor shrinkage in xenograft models derived from these organoids." (PMID 38673727, 2024). "The faster, softer, and less adhesive LGR5- cells likely have an advantage to escape the primary tumor and squeeze through the stroma to reach the vasculature." (PMID 38637494, 2024). "Rainbow tracing also validates that Lgr5+ tumor cells produce Lgr5+ cells and keratin 20 (KRT20)-positive mature cells, and thus have the ability to self-renew and differentiate, conferring Lgr5 as a marker of colorectal CSCs." (PMID 39872442, 2024).
tumor (continued). "To investigate the mechanisms orchestrating cancer stemness and tumour development, we analysed the transcriptional differences between differentiated (Krt20+Apoc2+Fabp2+) and stem (Lgr5+Cd44+Sox9+) cancer cells within tumours." (PMID 38658753, 2024). "The resulting subset of tumors follow distinct evolutionary paths compared with WNT/MYC-driven LGR5-derived tumorigenesis, and are characterized by an inflammatory tumor phenotype more prone to infiltration from the TME." (PMID 38902475, 2024). "After targeting Lgr5+ CSCs, proliferative Lgr5− cancer cells attempt to maintain tumor growth/regrowth to replenish the CSCs pool." (PMID 39183418, 2024). "Cancer stem cells (CSCs) are the driving force for tumor growth and, similar to ISCs (Lgr5+), fuel normal epithelium turnover." (PMID 38258906, 2024). "Irradiated male Lgr5+Apc1638N/+ mice showed the highest tumor incidence in 28Si (7.83 ± 1.10, n = 9) relative to γ-ray (4.73 ± 0.27, n = 15) or control (2.88 ± 0.17, n = 15) group." (PMID 39410012, 2024). "Key studies have revealed that the LGR5+ve stem cells within CRC tumours are also sensitive to injury through radiation and chemotherapy." (PMID 38319453, 2024). "The ablation of LGR5+ in intestinal cells limits tumor growth and metastasis; however, these events can resume through positive selection of cells that have regained LGR5 expression." (PMID 39324706, 2024). "Of note, anti-TIGIT immunotherapy prominently increased the CD90 and LGR5 expression in the tumor, which was markedly reversed by the addition of sulfarotene." (PMID 38543173, 2024). "Within the dysplastic regions of the tumour, we observe increased cellular LGR5 protein levels in >20% of β-catenin-expressing cells." (PMID 39169164, 2024). "In Lgr5+Apc1638N/+ mice, tumor incidence was significantly higher in those exposed to 28Si radiation compared to the spontaneous tumorigenesis observed in control mice." (PMID 39410012, 2024). "The adenocarcinoma regions of the tumour display a further increase in LGR5 protein levels (approximately two- to threefold) that are present in >95% of all cancer cells." (PMID 39169164, 2024). "We next probed the highly annotated Bern CRC tumour microarray (TMA) with α-LGR5 and α-β-catenin antibodies." (PMID 39169164, 2024). "In the high LGR5‐expression group, the histological grade was lower than in the low LGR5‐expression group (p = 0.0159), while necrosis was significantly more prevalent (p = 0.0326), and the tumor, node, metastasis stage was significantly lower (p = 0.0302)." (PMID 38787285, 2024). "Since its discovery, scientists have found that Lgr5+ cells in aggressive lesions of intestinal adenomas harbor CSC signatures and potentials, and are associated with tumor expansion and stemness." (PMID 38254219, 2024). "LGR5 + cells can revert to LGR5 − under drug treatment, and both populations can regenerate the tumor in vivo." (PMID 38329598, 2024). "When Lgr5+ CSCs are eliminated with DT treatment, tumor growth is moderately inhibited and recovers rapidly after drug withdrawal." (PMID 39872442, 2024). "Orthotopic transplantation of tumor organoids constructed from Lgr5+ CSCs into mice drove tumorigenesis, and targeted elimination of Lgr5+ cells inhibited tumorigenesis." (PMID 38254219, 2024). "Together, our data highlight the need for directly determining LGR5 protein levels in healthy and tumour tissues as a faithful indicator of tissue and tumour expression." (PMID 39169164, 2024).
tumor (continued). "Our results regarding EPHB2 and LGR5 stem-cell signatures support the importance of periostin for cancer stem-cell niches at the pericryptal regions for tumour development." (PMID 38532103, 2024). "It has been suggested that the LGR5+ve CSC population is replenished after therapeutic treatment by progenitor cell types that revert into a stem-like state to drive tumour regeneration through mechanisms of cellular plasticity." (PMID 38319453, 2024). "The percentage of Lgr5-expressing cells with c-Src phosphorylation in KO tumor tissues was decreased about twofold compared to AKP tissues." (PMID 39535280, 2024). "It has been suggested that a subpopulation of LGR5-expressing cancer stem cells (CSCs) is responsible for driving tumour relapse and therapy resistance in CRC." (PMID 38319453, 2024). "Given the high expression of LGR5 in NB tumor cells, we tested the potential of ADCs targeting LGR5 for the treatment of high-risk NB using the PBD class of the payload SG3199." (PMID 39065640, 2024). "We assigned 14 of the cancer types as ‘high LGR5 expressors’ defined by greater than 70% of component tumour biopsies as harbouring LGR5 expression levels greater than the pan-cancer median." (PMID 39169164, 2024). "Here, we wanted to detect the effect of 28Si ions in ISCs in normal and tumor tissue from the Lgr5+Apc1638N/+ mice model." (PMID 39410012, 2024). "Again, the remodeling of Lgr5+ cells into Lgr5− cells induces immune escape and tumorigenesis, echoing cell fate remodeling during tumor metastasis." (PMID 39872442, 2024). "In vivo experiments also proved that anti-LGR5-mc-vc-PAB-MMAE significantly reduced tumor volume, and it eliminated CSCs, achieving complete remission (no tumor detected), without inducing toxicity to the normal portion of the intestinal tract." (PMID 38254219, 2024). "Simultaneously, it exhibits strong anti-tumor activity in xenograft models derived from patients with high expression of Lgr5 and EGFR." (PMID 38140103, 2023). "We observed that LGR5‐expressing tumor cells will grow into organoid which surrounded closely by CAFs, within the direct cell–cell contact co‐culture model." (PMID 37578396, 2023). "These can eventually restore the pools of Lgr5+ CSCs, together with sustained tumor growth and liver metastasis." (PMID 37894295, 2023). "Knockout of LGR5 + cells leads to transient tumour regression, but KRT20 + tumour cells quickly differentiate into LGR5 + tumour cells." (PMID 37537666, 2023). "These LGR5-targeted ADCs target the LGR5-expressing population of tumor-initiating cells or cancer stem cells (CSCs)." (PMID 37190019, 2023). "The existence of CAFs upon engrafting tumor organoids resulted in dramatic higher number of LGR5+ cells in the neoplasia when compared with engrafting tumor organoids alone." (PMID 37578396, 2023). "Previous results have proved that CAFs can promote the growth of LGR5‐expressing cell to initiated tumor organoids and maintain their structure in an in vitro 3D culture system." (PMID 37578396, 2023). "Then, we found this tumor growth promoting effect was dramatically eliminated by DT treatment upon specific depletion of LGR5‐expressing cells." (PMID 37578396, 2023). "CAFs traced by red fluorescent protein (RFP) were isolated from co‐engraft tumors and GFP‐expressing LGR5‐expressing tumor cells were separated from both mono‐ and co‐engraft tumors." (PMID 37578396, 2023). "We further investigated the mutual interaction of LGR5‐expressing tumor cell and CAF in vivo within immunodeficient mouse model." (PMID 37578396, 2023). "In mouse models, genetic inactivation of the key colorectal cancer (CRC) driver gene Adenomatous Polyposis Coli (Apc) in Lgr5+ cells precipitated rapid tumor induction." (PMID 38140103, 2023). "On the other hand, Usp7 depletion in Lgr5 EGFP-IREScreApcfl/fl tumor model showed clear survival advantage, indicating that USP7 is an effective target for sporadic CRC." (PMID 36669491, 2023).